CRB2 (crumbs cell polarity complex component 2)
Diseases named in the same sentence as CRB2 in open-access papers (continued):
Sharing a sentence is not in itself a finding about the gene and the disease.
intrauterine growth restriction (1 paper, 2021). "In mice, the complete Crb2 knockout mice showed embryonic lethality, and in humans, intrauterine growth restriction has been reported." (PMID 34654837, 2021).
Microhematuria (1 paper, 2021). "Microhematuria was also more recognizable in Crb2fl/flpod-CreTg/+ mice than in Crb2+/+pod-CreTg/+ or Crb2fl/fl mice (1.42 ± 0.66 vs. 0 ± 0 or 0.08 ± 0.2, P < 0.0001 or P = 0.002)." (PMID 34654837, 2021). "Microhematuria was more recognizable in Crb2fl/flpod-CreTg/+ mice than in Crb2+/+pod-CreTg/+ or Crb2fl/fl mice (0.83 ± 0.68 vs. 0 ± 0 or 0 ± 0, P = 0.0083)." (PMID 34654837, 2021). "Therefore, microhematuria and albuminuria observed in our podocyte-specific Crb2 knockout mice are probably indicators of progressive tubulointerstitial fibrosis." (PMID 34654837, 2021).
nephrosis (1 paper, 2025). Pathological processes of the KIDNEY without inflammatory or neoplastic components. "Here, we report a novel homozygous pathogenic variant in the EGF-like domain of exon 7 of the CRB2 gene, associated with a broad multisystemic phenotype, including nephrosis, CNS abnormalities, and cardiac involvement." (PMID 40456931, 2025).
neuroblastoma (1 paper, 2022). Neuroblastoma (NB) is the most common solid, extracranial childhood tumor.
Nystagmus (1 paper, 2017). Rhythmic, involuntary oscillations of one or both eyes related to abnormality in fixation, conjugate gaze, or vestibular mechanisms. "Recently one patient with a CRB2 mutation has been reported, presenting with reduced visual acuity, nystagmus, and irregular retinal pigmentation." (PMID 28671996, 2017).
psoriasis (1 paper, 2017). An autoimmune condition characterized by red, well-delineated plaques with silvery scales that are usually on the extensor surfaces and scalp. "The four genetic variants—rs1802073 G>T in SFRP4, rs1105223T>C in CRB2, rs3821414T>C in ARHGEF3, rs11086065A>G in ANKLE1—could be validated as predictive markers for the response to acitretin in psoriasis." (PMID 28146080, 2017).
Retinal dysplasia (1 paper, 2022). Abnormal growth and differentiation, structure and appearance of the retina present from birth. "In vertebrate models, mutation or loss of zebrafish (Danio rerio) orthologs of apicobasal polarity proteins EPB41L5 (zebrafish moe), MPP5 (nok), and CRB2 (ome) cause retinal developmental and lamination abnormalities similar to Crb1-associated retinal dysplasia." (PMID 35675330, 2022). "Cx3cr1, Mthfr, and Cygb were identified as modifiers of Crb1rd8 retinal dysplasia, Jak3 as an enhancer of a Crb1rd8-dependent neovascular phenotype, and Crb2 as a modifier of retinal dysplasia due to a Crb1 knock-out allele." (PMID 35675330, 2022). "Deficits in mouse CRB1, CRB2, CRB1 and CRB2 combined, MPP5, and PRKCI have similar effects, supporting the hypothesis that defects in apicobasal polarity cause retinal dysplasia." (PMID 35675330, 2022).
tumor (5 papers, 2019 to 2026). "Finally, we conducted a gene network analysis of the DEFA gene and found that there were tumor-suppressor-related genes associated with DEFA, including FGF21 and ITLN1, as well as tumor-promoting genes associated with DEFA, including GNB3, CRB2, DIO3, HPD, and Dll3." (PMID 41009818, 2025). "Furthermore, Western blot analysis suggested that CRB2 may activate the Wnt/planar cell polarity (PCP) signalling pathway, contributing to tumour progression." (PMID 41906249, 2026). "Notably for FAT4, BFAR, CRB2, and PEX14, we did not identify somatic mutations in the wild-type allele of these genes in the cases carrying germline mutations, suggesting that if they are contributing to tumor formation, they most likely do not function as classical tumor suppressors." (PMID 31101826, 2019).
retinopathies (4 papers, 2017 to 2024). "Variants in the CRB1 gene have long been associated with retinopathies, and more recently the CRB2 gene has also been shown to have possible clinical relevance with respect to retinopathies." (PMID 28424578, 2017). "Then, we hypothesize that CRB2 gene might be a crucial candidate modifier for the severity of CRB1-associated retinopathies, and moderate levels of CRB2 could partially protect against the degeneration caused by CRB1 deficiency." (PMID 38802833, 2024). "In contrast, additional deletion of CRB2 in the CRB1 knockout retina exacerbates the retinal phenotype, suggesting that CRB2 putatively acts as a modifying factor of human CRB-associated retinopathies." (PMID 38802833, 2024). "The cause for the phenotypic variability in CRB1-associated retinopathies is unknown, but might be linked to differences in CRB1 and CRB2 protein levels in Müller glial cells and photoreceptor cells." (PMID 37886604, 2023). "For example, a mild decrease in CRB levels leads to a relatively milder form of retinopathy, whereas greater reductions in CRB1 and CRB2 lead to early-onset RP; finally, a complete lack of CRB1 and CRB2 leads to LCA." (PMID 28424578, 2017).
kidney diseases (3 papers, 2022 to 2025). "Since CRB2 is required for epithelial apical-basal differentiation, the loss of CRB2 function causes podocyte alterations leading to kidney diseases." (PMID 36556986, 2022). "Based upon CRB2 function, expression and previous association with kidney disorder, a variant in the gene was hypothesized to be the strongest candidate variant." (PMID 36556986, 2022).
brain diseases (1 paper, 2023). "Pathogenic variants in CRB2 have been identified in non‐syndromic autosomal recessive RP, with CRB2 playing a crucial role in photoreceptor survival, as well as syndromic kidney and brain diseases." (PMID 36656098, 2023).
CRB2 also shares sentences with these, for which no sentence is quoted: Aqueduct stenosis (2 papers); congenital hydrocephalus (2); nephropathies (2); B cell lymphoma (1); Cerebellar atrophy (1); cone-rod dystrophies (1); Gliosis (1); lupus erythematosus (1); Macular dystrophy (1); non-communicating hydrocephalus (1); ovarian cancer (1); renal failure (1).